RIPK3 (receptor interacting serine/threonine kinase 3)
Diseases named in the same sentence as RIPK3 in open-access papers (continued):
Sharing a sentence is not in itself a finding about the gene and the disease.
melanoma (continued). "In conclusion, we demonstrated here the epigenetic inactivation of RIPK3 in malignant melanoma by DNA hypermethylation of its promoter region/CpG island." (PMID 38397165, 2024). "The size of the nuclei decreased significantly by using RIPK3 wt in all melanoma cell lines examined." (PMID 38397165, 2024). "We observed a reduced fitness of melanoma cells by (re-)expression and demethylation of the RIPK3 gene using the epigenetic editing-based method." (PMID 38397165, 2024). "To investigate the methylation rate of the RIPK3 CpG island with advancing tumor progression, we quantified RIPK3 methylation by pyrosequencing of patient material of naevi, dysplastic naevi, primary melanomas, metastases, and melanoma cell lines." (PMID 38397165, 2024). "However, it was unclear how the loss of RIPK3 in melanoma could be explained." (PMID 38397165, 2024). "Although reactivation of RIPK1 and RIPK3 can lure necroptosis in a melanoma tumor cell to delay tumor progression, the correlation between necroptosis and melanoma still needs further exploration." (PMID 37147395, 2023). "Expression of RIPK3 is extremely low in melanoma development, but plays a permissive role inhibiting apoptosis proteins (IAP) antagonist-induced necroptosis in malignant melanoma." (PMID 37580654, 2023). "Although RIPK3 is lost in a panel of malignant melanoma cells and functions as a suppressor of melanomagenesis, it does not seem to play any role in our genetic model." (PMID 35422482, 2022). "For example, a RIPK3 V458M mutant was found in melanoma (COSMIC) that is potentially defective in its RHIM domain." (PMID 35422482, 2022). "Kinetics of Initiation and progression of melanoma was similar in the Ripk3 background as the Mlkl background." (PMID 35422482, 2022). "RIPK3 expression is lost in malignant melanoma and contribute to primary and therapeutic resistance of these cells to necroptosis." (PMID 35422482, 2022). "Silencing of the necroptosis initiator Ripk3 occurs in a wide variety of cancer types including melanoma." (PMID 35422482, 2022). "Several genes have been identified to be involved in the necroapoptotic process; for example, RIPK3 deletion has been shown to predict the necroapoptosis resistance process in malignant melanoma." (PMID 36523972, 2022). "The multivariate COX regression analysis suggested that RIPK3 is an independent prognostic factor in melanoma, along with patients' age (P=0.017), AJCC T stage (P < 0.001), and N stage (P < 0.001)." (PMID 35874627, 2022). "To the best of our knowledge, we are the first to demonstrate that CV extract can induce RIPK1/RIPK3/MLKL-mediated necroptosis in depigmented melanoma cells." (PMID 34072104, 2021). "Necroptosis has been reported to enhance anti-tumor immunity in colon cancer and melanoma and RIPK3 expression status is proposed to influence the clinical outcome of TLR3-based cancer immunotherapy." (PMID 33036630, 2020). "The expression of RIPK3 is decreased in patients with melanoma, breast cancer, and colorectal cancer, and high expression of RIPK3 in the tumors of these patients is strongly associated with survival." (PMID 33348858, 2020). "Several previous studies demonstrated that dabrafenib actually inhibits the RIPK3-mediated phosphorylation of MLKL in vitro using human melanoma cells, human dermal fibroblasts, human colon cancer cells, and leukemia cells." (PMID 31817643, 2019). "We found that 38 out of 39 melanoma cell lines that have an activating BRAF mutation are fully resistant to necroptosis and have lost RIPK3 expression." (PMID 30157175, 2018). "Given the marked effects of RIPK3 deficiency on NKT cell production of TNF and IFN-γ in the melanoma model, we next examined RIPK3 involvement in a model of inflammatory tissue damage." (PMID 26381214, 2015). "For this, WT or Ripk3−/− mice were injected first i.v. with B16 melanoma cells and then i.p. with either PBS or α-GalCer, and tumour nodules in the lungs were examined." (PMID 26381214, 2015).
melanoma (continued). "In summary, reconstitution of functional RIPK3 in melanoma cell lines increasingly promotes DL-induced apoptosis and unmasked DL-induced necroptosis in the absence of caspase and IAP activity." (PMID 26355347, 2015). "We further observed an altered cell death morphology in melanoma cells with functional RIPK3, whenever caspases are blocked." (PMID 26355347, 2015). "To functionally investigate the role of RIPK3 in apoptotic and necroptotic cell death in melanoma, we next reconstituted RIPK3 in a number of melanoma cell lines." (PMID 26355347, 2015). "In line with the recent report, Dabrafenib but not Vemurafenib blocked necroptosis (black bars) and MLKL phosphorylation, but also protected from DL/IAP antagonist-mediated apoptosis (grey bars) in RIPK3-reconstituted A375 or IGR melanoma cells." (PMID 26355347, 2015). "We next analysed the respective RIPK3-expressing melanomas for DR-induced, caspase-dependent or -independent cell death." (PMID 26355347, 2015). "In this study, we demonstrate that RIPK3-mediated signalling regulates the activation of NKT cells in mouse models of melanoma and acute inflammatory liver injury." (PMID 26381214, 2015). "Indeed, while tumor cell lysates isolated from in vivo growing B16 melanomas showed strong RIPK3 expression, short-term tumor cell culture and in particular prolonged in vitro passaging resulted in rapid loss of RIPK3 but not MLKL protein expression." (PMID 40345706, 2025). "Our methylation analyses of the RIPK3 CpG island, located downstream of its promoter, showed the successive hypermethylation from primary tumors to cancer cell lines, in general, but also in primary malignant melanoma." (PMID 38397165, 2024). "Several investigations have reported that the potential to trigger necroptosis in melanoma might be inhibited due to low expression levels of both CYLD and RIPK3 in melanoma cell lines." (PMID 38336727, 2024). "Our work, therefore, investigated the possible epigenetic regulation of RIPK3 in melanoma." (PMID 38397165, 2024). "Based on the metadata, we investigated the epigenetic silencing of RIPK3 in melanomas." (PMID 38397165, 2024). "Our results show that VP160-dCas9 was able to cause re-expression in the melanoma cell line MeWo and kidney cell line HEK, whereas RIPK3 demethylation could only be observed in HEK." (PMID 38397165, 2024). "In conclusion, RIPK3 resists pharmacological demethylation treatment in melanoma." (PMID 38397165, 2024). "Indeed, the downregulation of RIPK3, which is commonly found in melanoma cells, correlated with a poor prognosis and was found to enhance tumor progression and cancer metastasis." (PMID 39349444, 2024). "However, direct intramelanoma delivery of either the RIPK3 gene via adenovirus or mRNA encoding MLKL, a necroptosis executioner, elicited both necroptosis and potent antitumor immunity in melanoma model mice." (PMID 38336727, 2024). "In addition, an increasing RIPK3 methylation rate was observed with increasing tumor stage of melanomas." (PMID 38397165, 2024). "We overexpressed RIPK3 KD (kinase dead) and RIPK3 wt (wild type) in four melanoma cell lines." (PMID 38397165, 2024). "Indeed, Ripk3−/− mice have reduced endothelial permeability affecting tumor migration into the lung using a B16 melanoma model." (PMID 35351865, 2022). "The increased expression of ZBP1 and RIPK3 also happens in mouse melanoma B16, mouse lung cancer LLC, human breast cancer MCF-7 and MDA-MB-231 tumors as their expression levels are significantly higher in the cells from tumors compared to that in the cultured parental cells." (PMID 33976222, 2021). "Dabrafenib disrupted RIPK3 and MLKL interactions that was associated with decreased levels of MLKL phosphorylated at Ser358, and prevented from induction of necroptosis in RIPK3-expressing melanoma cells." (PMID 32340261, 2020).
melanoma (continued). "Thus, according to our findings, RIPK3 expression is expected to be induced in most anti-melanoma therapies that employ mutant BRAF-specific inhibitors." (PMID 30157175, 2018). "Furthermore, wild-type mice inoculated with B16 melanoma were able to clear the tumor burden upon administration of αGC, but RIPK3−/− mice were unable to do so, suggesting that RIPK3 is essential in iNKT-mediated anti-tumor responses." (PMID 29326711, 2017). "Our data suggest that loss of RIPK3 in melanoma and selective inhibition of the RIPK3/MLKL axis by BRAF inhibitor Dabrafenib, but not Vemurafenib, is critical to protect from necroptosis." (PMID 26355347, 2015). "However, CD95L-induced cell death in RIPK3-expressing melanoma cells or their respective controls was unaltered by addition of TNFR2-Fc." (PMID 26355347, 2015). "Our data presented in the current study indicate that a combination therapy of Dabrafenib or Vemurafenib together with reagents that allow RIPK3 reconstitution could be such a strategy that was tested in vitro in melanoma." (PMID 26355347, 2015). "When we examined the cause for loss of necroptosis, we uncovered the vast absence of RIPK3 protein expression in melanomas when compared with melanocytes and nevus cells." (PMID 26355347, 2015). "Strategies that allow RIPK3 expression may allow unmasking the necroptotic signalling machinery in melanoma and points to reactivation of this pathway as a treatment option for metastatic melanoma." (PMID 26355347, 2015). "Therefore, functional RIPK3 is necessary for apoptosis and necroptosis execution in malignant melanoma." (PMID 26355347, 2015). "Reactivation of the RIPK1/RIPK3/MLKL signalling platform by RIPK3 reconstitution can overcome necroptosis resistance in melanoma and therefore could be used as potential death-inducing targeted therapy against melanoma." (PMID 26355347, 2015). "We believe that RIPK3 may serve as a cancer biomarker for melanoma in the future." (PMID 38397165, 2024). "In addition, we showed the tumor suppressive role of RIPK3 in melanoma upon its re-induction." (PMID 38397165, 2024). "Furthermore, these results were consistent with previous studies and provided more shreds of evidence in the potential ability of RIPK3 to serve as a novel target in melanoma, especially in enhancing “hot” tumor phenotype and improving the efficacy of existing immunotherapies." (PMID 35874627, 2022). "Accordingly, both loss of RIPK3 in the tumor microenvironment and loss of the kinase activity in RIPK1 have been reported to reduce tumor nodules in the lung in murine B16.F10 primary melanoma tumors, which further implies that RIPK3 and RIPK1 are fundamental for cancer growth and metastasis." (PMID 33665167, 2020). "In addition, inhibition of RIPK1 and loss of RIPK3 did not reduce lung metastasis in a mouse model of melanoma." (PMID 32340261, 2020). "Necroptosis, governed by the receptor-interacting protein kinase 1 (RIPK1)/RIPK3 mixed lineage kinase domain-like protein (MLKL) signaling axis, can synergize with immunotherapy to enhance anti-melanoma immune responses when activated." (PMID 40497999, 2025). "In summary, we were able to reestablish the tumor suppressive function of RIPK3 not only in HEK, but also in melanoma cell lines." (PMID 38397165, 2024). "In malignant melanoma and CRC, RIPK3 can interact with ZBP1 through RHIM, driving the recruitment of caspase-6 and caspase-8 to form the ZBP1–PANoptosome complex, which activates the NLRP3 inflammasome and induces PANoptosis." (PMID 38684668, 2024). "In all melanoma cell lines and HEK with transfected RIPK3 wt, the cells were small and round and had less-structured nuclei and cell protrusions." (PMID 38397165, 2024). "The results show a significant deterioration of cell morphology in the cell lines C918, IGR1, MeWo, SkMel13 (all melanomas) and HEK after RIPK3 wt overexpression, which was characterized by reduced cell nuclei and reduced nuclear fitness." (PMID 38397165, 2024).
melanoma (continued). "In melanoma cells actively engaged in melanogenesis, the use of melanin synthesis inhibitors to induce depigmentation has shown to restore sensitivity to RIPK1/RIPK3/MLKL-mediated necroptosis." (PMID 38036577, 2023). "Reconstituting RIPK3 can reactivate the RIPK1/RIPK3/MLKL signaling pathway, which can eventually overcome the resistance of melanoma to necroptosis." (PMID 37580654, 2023). "In another study, pretreatment with BAY 87-2243, a specific inhibitor of mitochondria complex-I, triggered ROS generation, mitochondrial dysfunction and mitophagy, following RIPK3/MLKL activation and induction of necroptosis in BRAFV600E melanoma cells." (PMID 36361505, 2022). "Further studies revealed that in amelanotic melanoma cells, PBPs-induced death is related to inducing the RIPK1/RIPK3/MLKL-mediated necroptosis." (PMID 35359389, 2022). "In melanoma cells with active melanogenesis, induction of depigmentation with a melanin synthesis inhibitor restores melanoma cell sensitivity to RIPK1/RIPK3/MLKL-mediated necroptosis." (PMID 35610275, 2022). "We co-cultured CV-stimulated depigmented melanoma cells with selected kinases inhibitors: necrostatin-1 (Nec-1), GSK’872 and necrosufonamide (NSA), which specifically target RIPK1, RIPK3, and MLKL activity, respectively." (PMID 34072104, 2021). "Related to the mechanism of action, our results show that CV extract induce RIPK1/RIPK3/MLKL-dependent necroptosis, in the depigmented melanoma cells, which serves as an alternative mode of programmed cell death to eradicate apoptosis-resistant cancer cells." (PMID 34072104, 2021). "The viability of melanoma cells depigmented with 10−3 M d-pen, 6 μg/mL KA, or 30 μg/mL KA increased after CV stimulation when the RIPK1, RIPK3, and MLKL kinases were inhibited." (PMID 34072104, 2021). "It has been shown that RIPK3-expressing melanoma cells were sensitive to necroptosis-inducing agents and cell death could be efficiently inhibited by necrostatin-1, although gaining competence to trigger necroptosis upon overexpression of RIPK3 has been questioned by others." (PMID 32340261, 2020). "As demonstrated for TNF-mediated necroptosis, RIPK3-expressing A375 or, to a lesser extent, IGR melanoma cells (lower result panel), but not control transduced melanoma cells, were not fully protected from IAP antagonist/CD95L treatment by ZVAD-fmk and Nec-1." (PMID 26355347, 2015). "We report here that although cotreatment with HDAC and BRAF inhibitors activates the caspase cascade and the mitochondrial apoptotic signaling, it kills BRAFV600E melanoma cells predominantly by induction of necrosis in a RIPK1- and RIPK3-independent manner." (PMID 23744355, 2013). "Collectively, these results indicate that the combination of SAHA and PLX4720 induces necrosis of melanoma cells independently of RIPK1 and RIPK3." (PMID 23744355, 2013). "Therefore, even when RIPK3 and MLKL are normally expressed, TAK1 can still prevent melanoma cell death." (PMID 40497999, 2025). "However, in contrast to B16 melanoma, MOC1 cells showed consistently strong RIPK3 expression levels during in vitro culture." (PMID 40345706, 2025). "In the melanoma cells, possibly due to the moderate methylation of RIPK3, TET1-dCas9 did not induce its epigenetic reactivation." (PMID 38397165, 2024). "We did not observe significant demethylation of RIPK3, despite efficient reactivation of other tumor suppressor genes using our established Aza treatment condition, in other studies also in melanoma." (PMID 38397165, 2024). "The downregulation of RIPK3 and MLKL may contribute to a poor prognosis in multiple cancers (such as breast cancer, melanoma, colorectal cancer and acute myeloid leukaemia)." (PMID 37580654, 2023). "However, the specific regulatory pathways of USP30-AS1 interfering with RIPK3 and MLKL in melanoma still need further investigation." (PMID 37147395, 2023).
melanoma (continued). "Full Ripk3−/− mice did not behave differently from littermate Ripk3+/+ mice in the BrafV600EPten−/− melanoma model." (PMID 35422482, 2022). "RIPK1, RIPK3, and MLKL might have different necroptosis-(in)-dependent roles during melanoma development." (PMID 35422482, 2022). "Unlike MLKL the necroptosis-regulator RIPK3 does not seem to have any impact on melanoma progression in this model." (PMID 35422482, 2022). "In addition, reduced RIPK3 expression was also found in clinical samples from human cancer patients, such as colorectal, breast, acute myeloid leukemia (AML), and melanoma." (PMID 36361505, 2022). "RIPK1 is described as an oncogenic driver in melanoma due to its scaffold function independent of the kinase function, while RIPK3 expression apparently is suppressed by the BRAF and AXL oncogenes." (PMID 35422482, 2022). "Investigating the role of the RIPK3 expression regain in cancer resistance and tumor regrowth in patients following BRAF inhibitor therapies (e.g., melanoma) could be of importance to explain this clinically vital phenomenon." (PMID 30157175, 2018). "Taken together, these observations raised the possibility that the lack of RIPK3 mRNA and protein expression explains the absence of necroptosis in melanoma cells." (PMID 26355347, 2015). "In marked contrast, RIPK3 mRNA expression was absent or below detection level in all melanoma cell lines studied." (PMID 26355347, 2015). "Reconstitution of RIPK3, but not a RIPK3-kinase dead mutant in a set of melanoma cell lines overcame CD95L/IAP antagonist-induced necroptosis resistance independent of autocrine tumour necrosis factor secretion." (PMID 26355347, 2015). "MLKL phosphorylation was detected in a time-dependent manner within 90 min, with further increase up to 6 h after stimulation in RIPK3-expressing, but not in RIPK3-KD or vector control melanoma cells." (PMID 26355347, 2015). "On the one hand, the downregulation of RIPK3 or MLKL is related to poor prognosis of various types of cancer, such as breast cancer, colorectal cancer, acute myeloid leukemia, head and neck squamous cell carcinoma, melanoma, cervical squamous cell carcinoma, gastric cancer, and ovarian cancer." (PMID 34977874, 2021). "Several studies have indicated that inducing necroptosis in melanoma may be limited as it was found that both CYLD and RIPK3 were poorly expressed in melanoma cell lines, although melanocytes and benign nevi expressed RIPK3 at a high level." (PMID 32340261, 2020). "Therefore, strategies that increase RIPK3 expression in combination with Vemurafenib, but not Dabrafenib, likely represent an attractive strategy to overcome cell death resistance in melanoma." (PMID 26355347, 2015). "Interestingly, RIPK3-expressing melanoma cells, but not RIPK3-KD cells, show spontaneous and increased MLKL phosphorylation, a strong indication that kinase activity of RIPK3 is the missing link for DL-mediated necroptosis in melanomas." (PMID 26355347, 2015). "Furthermore, the inhibitor of mutant BRAF Dabrafenib, but not Vemurafenib, inhibited necroptosis in melanoma cells whenever RIPK3 is present." (PMID 26355347, 2015). "In the B16 melanoma model, intratumoral application of low-dose AZA without direct cytotoxic effects did increase transcriptional activity of both Ripk3 and Mlkl in tumor cells in vivo." (PMID 40345706, 2025). "Then, we discovered that the inhibitors of RIPK1, RIPK3, and MLKL kinases diminished the intracellular ROS generation triggered by CV compounds in non-pigmented melanoma cells." (PMID 34072104, 2021). "In marked contrast, expression of RIPK3 is extremely low (A375, MC, IGR, and MM-LH) or fully absent in melanoma cells." (PMID 26355347, 2015). "This supports that neither apoptosis nor necroptosis in RIPK3-expressing A375 and IGR melanoma cells is dependent on autocrine TNF signalling." (PMID 26355347, 2015).